CD44 (CD44 molecule (IN blood group))
Diseases named in the same sentence as CD44 in open-access papers (continued):
Sharing a sentence is not in itself a finding about the gene and the disease.
cancer (continued). "The function of CD44 in cancer is not only dependent upon CD44 expression levels, as recent studies demonstrated that many polymorphisms in CD44 were correlated with the risk of several types of cancer." (PMID 37958796, 2023). "CD44 is a ubiquitous cell surface adhesion receptor that has been shown to be a marker of some stem cells, metastatic cancer cells, and interestingly, memory T-cells." (PMID 37622115, 2023). "In contrast to the research studies focused on the role of CD44+EVs in cancer, studies on the role of these EVs in trauma and/or hemorrhage are very rare." (PMID 37662913, 2023). "Crucially, knockdown of CD44 decreases the adhesiveness of human colon cancer cells to HA, cancer-colony-forming ability, and xenograft tumorigenicity, while increasing susceptibility to etoposide-induced apoptosis." (PMID 37958796, 2023). "The knockdown of PFKFB3 inhibits the expression of cancer stemness markers such as CD133, ALDH1A1, CD44, Sox2, and ABCG2, which are also associated with chemotherapy resistance." (PMID 37919747, 2023). "CD44 is a transmembrane glycoprotein expressed on the surface of a variety of cells, including cancer cells." (PMID 37958796, 2023). "CD44 has recently been introduced as a cancer stem cell marker in various types of cancers, including renal cell carcinoma." (PMID 36835190, 2023). "The authors injected CD44+CD24+/ESA+ cancer cells in immunocompromised mice and observed a 100-fold increase in tumorigenic potential when compared to those mice injected with nontumorigenic cancer cells." (PMID 36776295, 2023). "The pro-migratory mechanisms of HA/CD44 are likely different in epithelial and mesenchymal cells and, hence, in carcinomas vs. sarcomas." (PMID 37958796, 2023). "With the HA residues on the outer surface, FeIIITA@HA nanoprobes can specifically target the SCC cells through the over-expressed CD44, and accumulate in the carcinoma region after intravenously administration." (PMID 36597067, 2023). "Conversely, the ability of SPP1+ macrophages to influence carcinoma cell identity appeared to correlate with expression levels of CD44, the Osteopontin receptor." (PMID 38036590, 2023). "Because CD44 is related to cancer stemness and cancer malignancy, the regulatory effect of Sp1 on the level of CD44 was studied." (PMID 35034634, 2022). "The HKCI-C1 vector control cells and CD44E/s cells, and three cell lines with negligible CD44 expression, including a normal liver cell line MIHA and two live cancer cell lines Hep3B and Huh7, were lively stained with Cy5-CD44-Apt1 or aptamer library." (PMID 34976591, 2022). "These issues must be addressed before targeted CD44 glycosylation can be applied to treat human cancers." (PMID 35936713, 2022). "Alternative splicing can produce many CD44 isoforms that possess various tissue-specific effects during cancer progression." (PMID 36292918, 2022). "Conversely, the mesenchymal markers fibronectin, N‐cadherin and vimentin, the EMT‐TFs Snail, Slug, Zeb1 and Zeb2, and the cancer stem cell markers CD44, Sox2 and Id1 were strongly induced by TGFβ and repressed by BMP in 3D cultures." (PMID 35348275, 2022). "The researchers encapsulated miR-34a into nanoscale PEGylated liposomal vesicles to target CD44-positive cancer cells." (PMID 36182897, 2022). "CD44 is a receptor for hyaluronan and plays a central role in cancer by triggering signals that induce cell migration and invasion." (PMID 35207132, 2022). "The top outgoing signaling from epithelial cancer cells to CAFs (communication probability > 0.10) showed interactions between MIF (cancer cells) and CD74 + CD44 (CAFs) or MDK (cancer cells) and NCL/SDC2/LRP1 (CAFs)." (PMID 36352420, 2022). "CD133 and CD44 are also adherent molecules and are shown to be important stem biomarkers for colon and other cancers." (PMID 36612229, 2022).
cancer (continued). "As noted, except for the crucial effects of CD44 in exosome biogenesis and therapeutic function in cancer, the role of CD44 in exosome biogenesis and its angiogenic function in MI injury have not been well elucidated and deeply discussed." (PMID 36463112, 2022). "As a cell adhesion molecule, CD44 has been validated as the content transported by exosomes and mediates the functions of recipient cells in cancer." (PMID 36463112, 2022). "In CD133+/CD44+ prostate CSCs, VCAN causes the suppression of cancer cell attachment to fibronectin and thereby increases cell motility." (PMID 36358747, 2022). "Trans-endothelium migration and invasion of cancer cells occur into the MVN stroma through binding of the isoform CD44 to the subendothelial ECM components." (PMID 35158914, 2022). "TNBC is known to be a representative radiation-resistant tumor because of its self-renewal and regeneration characteristics, similar to cancer stem cells, based on the expression of cell surface markers CD44+CD24− and aldehyde dehydrogenase 1 (ALDH1)." (PMID 36555137, 2022). "For example, CD44-shRNA adenovirus blocked Akt phosphorylation, which is responsible for the survival of cancer cells, and inhibited GSK-3b, which regulates several proteins responsible for cell proliferation." (PMID 36415383, 2022). "Preclinical studies using anti-CD44 antibodies to treat cancer have shown promising results, yet failing the clinical trials examining the safety and efficacy of anti-CD44 therapies." (PMID 35767191, 2022). "To this end, we first searched in the Cancer Cell Line Encyclopedia (CCLE) for cancer cells with a high expression level of CD44 mRNA." (PMID 36231028, 2022). "Based on the analysis of the individual cancer stage, the expression of CD44 was significantly different in stages 2, 3 and 4 (P < 0.0001)." (PMID 36316684, 2022). "In summary, the CD44 and NRP1 inhibitors to treat cancer patients with high-risk scores are promising." (PMID 36389678, 2022). "CD44 plays an important role in the invasion and metastasis of cancer cells and in basic biological processes, such as lymphocyte homing, hematopoiesis, inflammation, wound healing, and apoptosis." (PMID 35453596, 2022). "In the meantime, atropine reduced the protein levels of CD-44 and c-Myc, upregulated after treating both cancer cell lines by TGF-β." (PMID 36077256, 2022). "For instance, previous study indicated that OTUB1 directly interacted with SLC7A11, which facilitated CD44-mediated effects on ferroptosis in human cancers." (PMID 35354355, 2022). "The resultant formulation of HA-mExo-miR204 was able to specifically target CD44-positive cancer cells, with a concomitant increase in the intracellular uptake of miR-204." (PMID 36231028, 2022). "The expression of CD44, a cell surface marker of cancer stem-like cells in epithelial tumors, was evaluated using quantitative reverse transcription PCR." (PMID 36363571, 2022). "The cell line Detroit 562 showed the highest levels of PKM2 phosphorylated at Tyr105, corresponding with the highest expression of the cancer stem cell marker CD44." (PMID 35054968, 2022). "These nanoparticles restored drug sensitivity in CD44-overexpressing cancer cells in vitro, and inhibited tumor growth by 77% in vivo while eliminating the systemic toxicity of doxorubicin." (PMID 35626078, 2022). "The underlying mechanism includes the ASPN-mediated activation of Rac1 in both CAFs and cancer cells through its interaction with CD44." (PMID 36358747, 2022). "Three clear examples are Cd44, Celf2, and Taok3 which are overall highly expressed in the process and related to cell adhesion or cancer progression." (PMID 36329018, 2022). "Concordantly, high BGN expression was detected in MCF-7 derived CD24−/CD44+ BCSCs as compared to their respective bulk cancer cells." (PMID 35053617, 2022). "The different functional roles of CD44 isoforms in relation to cancer development and progression are under investigation." (PMID 35931675, 2022).
cancer (continued). "CD44, a cell surface integral membrane glycoprotein, is expressed in cancer cells and is admitted as a molecular marker for cancer stem cells." (PMID 36079127, 2022). "In this work, simultaneous detection of two cancer biomarkers, namely CD44 (a cell-surface glycoprotein) and HER2 (human epidermal growth factor receptor-2), has been performed." (PMID 36421126, 2022). "DMSNs3@HA is a DC-like nanoparticle modified with hyaluronic acid to target CD44 overexpressed on cancer cells, and conjugated with anti-CD3, anti-CD28 to interact with T cell, and anti-PD-1 to block the PD-1/PD-L1 pathway." (PMID 35967869, 2022). "All these results indicate that CD44 is an important regulator of cancer cell metastasis and a potential drug target." (PMID 34939255, 2022). "The inducible T-cell co-stimulator ligand (ICOSLG), a member of the B7 family of ligands, was found in mesenchymal GSCs, which expressed CD44, a cell surface marker of cancer stem-like cells in epithelial tumors." (PMID 36363571, 2022). "When adenovirus-mediated RNAi technology was used to knockdown the expression of Mcl-1 in GC, CD44+ cancer stem cell (CSC)-like cells became sensitized to chemotherapeutic agents such as 5-fluorouracil (5-FU) and cisplatin (CDDP)." (PMID 36505792, 2022). "And in HeLa, high expression of EMT marker Twist can induce EMT and elevate the expression of CD44 which is cancer stem marker of CSCs." (PMID 36685972, 2022). "On the other hand, a broader screening of main oncogenic pathways reflects another level of regulation dictated by the type of CD44 glycosylation, which appears to be key for defining oncogenic pathways adopted by cancer cells to support cancer aggressiveness." (PMID 35547758, 2022). "This DDS was delivered to cancer cells with CD44 overexpression owing to the targeting ability of HA towards CD44, and then released Zr (IV)-based porphyrinic MOF and CHC for enhanced photodynamic therapy (PDT) effect." (PMID 36627891, 2022). "CD44 overexpression interferes with the cytotoxic effects of chemotherapeutic drugs in various types of cancer." (PMID 36293491, 2022). "CD44, a representative marker for stem cells of several cancer types, is an adhesion molecule that binds to the extracellular matrix, mainly hyaluronic acid, and has been implicated in cancer cell migration, invasion, and metastasis." (PMID 36555827, 2022). "Since organoid-forming capacity is one of the hallmarks of cancer stemness, we assessed this trait by sorting for CD44+/CD24− population." (PMID 35406578, 2022). "Subcluster 3 expressed limited epithelial marker of EPCAM but cancer stem cell marker CD44 and NOTCH2." (PMID 35733218, 2022). "Internalization triggered by CD44-HA binding can prevent CD44 overexpression in cancer cells, making it possible to distribute anticancer drugs." (PMID 36277338, 2022). "The differences thus observed according to the type of tissue or cancer would come from the amount of HA or from the specificity of the different isoforms of CD44 for this molecule." (PMID 35406498, 2022). "For example, Tra2-β was found to promote the occurrence of cancer by affecting the AS events of CD44." (PMID 35126520, 2022). "We characterized the Panc1 cancer stem cells through the expression of canonical surface stem cell markers, namely CD44, CD24, and ESA." (PMID 35634239, 2022). "Combining HA with CD44 is one of the most important uses of HA in drug delivery systems because of the high level of CD44 expression on cancer cells and inflammatory macrophages." (PMID 35456573, 2022). "TIMP-3 is the only TIMP able to block both shedding mechanisms, thus regulating CD44 signalling in cancer progression." (PMID 35207132, 2022). "A plethora of cancer-associated markers such as CD133, CD44, ABCG2, aldehyde dehydrogenase, octamer binding transcriptional factor 4, SOX2, and NANOG have been reported in cancer stem cells." (PMID 35992863, 2022).
cancer (continued). "In another study, the coating of HA, a ligand for CD44, onto the surface of Au nanocages resulted in the specific recognition and targeting of cancer cells with overexpression of CD44." (PMID 36557793, 2022). "As a good example, CD44 has been used as a critical cancer cell/CSC therapeutic target for targeted drug delivery and cancer therapy." (PMID 36612229, 2022). "The endothelium moved into selectins, cadherins, integrins, and CD44, among other ligands and receptors involved in cancer cell adhesion." (PMID 36550571, 2022). "CD44 is a marker of cancer stem cells (CSCs), which accounts for a relatively small proportion of cancer cells." (PMID 35155251, 2022). "HA/CD44 interaction is central to the invasion which is why cancer cells express these receptors greatly." (PMID 36712656, 2022). "It was found that CD44 shedding by MT1-MMP promoted cancer cell migration on the HA-based substratum." (PMID 36132127, 2022). "Since CD44 is expressed in both embryonic stem cells and cancer cell subpopulations, it is also recognized as a molecular marker for cancer stem cells." (PMID 35163233, 2022). "The differences in the expressions of the hyaluronic acid receptor (CD44) in different cells affect the amount of drug accumulation in cancer cells." (PMID 36015667, 2022). "The expression levels of CD44, Lgr5, and Nanog were high in MKN28 cells compared with those in MKN45 cells, suggesting that viperin expression in the cancer cell lines was associated with CSCs." (PMID 36227691, 2022). "CD44, a transmembrane cell surface glycoprotein, has been show to play key roles in inflammatory responses and in cancer metastasis." (PMID 36346211, 2022). "They survive and maintain CSCs by activating the phosphatase and tensin homolog (PTEN)/PI3K/AKT signaling pathway, which is important for maintaining the CD44+/CD133+ cancer stem cell phenotype." (PMID 36012604, 2022). "The high-level expression of CD44, a cancer stem cell marker, was confirmed by fluorescence microscopy in LIU-LSC-1 cells." (PMID 36438491, 2022). "It has been suggested to regulate the crosstalk between inflammation and autophagy by evoking a switch between pro-inflammatory CD14 and pro-autophagic CD44 co-receptors for TLRs relevant to cancer progression." (PMID 35267503, 2022). "The Cluster of Differentiation (CD44) is a family of single-pass transmembrane glycoproteins known as a vital prognostic marker of several cancers." (PMID 36359337, 2022). "Several of the most commonly used cancer stem cell biomarkers are CD44, CD24, CD133, CD166, and ALDH1." (PMID 36184654, 2022). "CD44 regulates several signaling pathways to promote cancer progression, including Notch, Hedgehog (HH), Wnt, STAT3, Hippo, JNK, and RhoGTPase, and is a coreceptor that mediates signaling pathways by receptor tyrosine kinases." (PMID 35719973, 2022). "The concomitant overexpression of CD147 and CD44 makes the cancer stem cells present in OSCCs very viable and invasive." (PMID 35955471, 2022). "Different isoforms of CD44 are expressed according to the type of cancer, and cancers with different isoforms have been shown to be more aggressive than those with only CD44s." (PMID 35406498, 2022). "The most expressed of these includes variable exon 5 (see CD44 part in cancer), and its appearance depends on the Sam68 RNA binding protein." (PMID 35406498, 2022). "CD44 is a cell-surface glycoprotein with a postulated role in cancer metastasis with binding domains for hyaluronan and other glycosaminoglycans, collagen, laminin, and fibronectin, all components of the ECM." (PMID 34693476, 2022). "Conjugation of drug or drug-loaded nano-carriers with HA increases cancer cell uptake via CD44-mediated endocytosis." (PMID 35762636, 2022).
cancer (continued). "CD44 is a well-known membrane-bound receptor for ECM components that plays a major role in cancer progression and metastasis." (PMID 36148042, 2022). "This nanoformulation was orally administered to mice injected with triple-positive (EpCAM, CD133, and CD44) colon cancer stem cells in a xenograft cancer stem cell mouse model." (PMID 35264972, 2022). "Our findings are consistent with a previous report showing that CD44 enhances the glycolytic pathway during cancer progression." (PMID 35954411, 2022). "In vitro research has identified higher Gln in cancer stem cells with CD44(+) expression compared to CD44(−), with Gln additionally related to glutamate and Notch signaling via glutaminase, while CD133(+) appears to be linked to Gly." (PMID 35565293, 2022). "Our study showed that PFK158 attenuates sphere formation, migration/invasion and KLF4 mRNA expression, and enhances the sensitivity of ALDH+CD44+ cancer cells." (PMID 35155224, 2022). "Among such cell surface candidates, CD44 is a glycoprotein overexpressed in numerous cancers and which binds to its ligand hyaluronic acid." (PMID 36430705, 2022). "Concordantly, glucose deprivation, which robustly induced NNMT expression in the OVCAR3 cell line, increased the proportion of CD44-expressing cancer stem-like cells." (PMID 35756670, 2022). "Clarke’s group, CD44 has also been demonstrated to be a marker of Cancer Stem Cell (CSC) phenotypes in solid tumors." (PMID 35805061, 2022). "CD44 is a transmembrane glycoprotein and regulates cancer development and progression, which is overexpressed in many types of tumors and closely associated with a worse prognosis." (PMID 36678534, 2022). "The present analysis found elevated expression of CD47 not only positively correlated with PD1, PD-L1, CTLA4, but also with multiple other immune checkpoints such as IDO1, CD40, CD160, CD86, CD44 across various cancer types." (PMID 35697717, 2022). "These cell populations were further analyzed by using Lamp1PM expression in combination with a set of canonical markers distinct for cancer and stromal cells (i.e., desmin, Ki67, Sca1, Sma, Pcam1, CD44, Lyve1, and EpCam)." (PMID 36127469, 2022). "Mechanically, exosome-transferred MMP14 promotes the stability of CD44, the cancer stem cell marker in the recipient cells." (PMID 35223528, 2022). "Increased CD44 expression has been noted in multiple cancers such as pancreas, stomach, colon, lung, breast, prostate, salivary glands, and head and neck, among others, and has been linked to worse prognosis." (PMID 35296132, 2022). "The EMT is documented to endow HNSCC cells with properties of cancer stem cells (CSCs), including the enrichment of the CD44+/CD24− population of cancer cells and an increased expression of CSC-related genes." (PMID 35806389, 2022). "CD44 protein is involved in several cellular functions, including cell–cell and cell–matrix adhesion, as well as migration, which are critical steps in cancer progression and metastasis." (PMID 36079127, 2022). "CD44 is a transmembrane protein with a molecular weight of 85–200 kDa present in human cells, embryonic stem cells, cancer cells, and cancer stem cells." (PMID 36004971, 2022). "Due to the enhanced cellular uptake mediated by T22 targeting CXCR4 and HA targeting CD44 in malignant cells, our delivery vector can target cancer cells as well as CTCs in whole blood to realize efficient genome editing and mRNA detection." (PMID 35595716, 2022). "Then, we found that the combined expression of classical cancer stem markers (CD44, ABCG2, and ALCAM) can be used to predict the prognosis of LUAD." (PMID 36613925, 2022). "A specific target of TG2 in this model was the hyaluronan receptor CD44 expressed on cancer cells, which was upregulated in response to TG2 in the peritoneal environment." (PMID 35681474, 2022).